PHLDA3 (pleckstrin homology like domain family A member 3)
Description:
Represses AKT1 by preventing AKT1-binding to membrane lipids, thereby inhibiting AKT1 translocation to the cellular membrane and activation. May act as a tumor suppressor.
Synonyms: TIH1
Tractability: Antibody: UniProt places it where antibodies can reach, with high confidence; its Gene Ontology location is reachable by antibodies, with high confidence. PROTAC: ubiquitination databases record sites on it.
Gene: Protein-coding gene on chromosome 1 (201,464,278 to 201,469,237, reverse strand). Ensembl gene ENSG00000174307.
Subcellular location: Cytoplasm; Membrane
Gene Ontology:
Molecular function: phosphatidylinositol-3,4,5-trisphosphate binding; phosphatidylinositol-3,4-bisphosphate binding; phosphatidylinositol-3,5-bisphosphate binding; phosphatidylinositol-3-phosphate binding; phosphatidylinositol-4,5-bisphosphate binding; phosphatidylinositol-5-phosphate binding; phosphatidylinositol phosphate binding
Biological process: negative regulation of phosphatidylinositol 3-kinase/protein kinase B signal transduction; positive regulation of apoptotic process; anatomical structure morphogenesis
Cellular component: plasma membrane; cytoplasm; membrane
Genetic constraint (gnomAD): Loss-of-function variants: 12 observed, 7.61 expected, observed/expected ratio (o/e) 1.58, 90% interval 0.96 to 1.94. That is too few expected variants to judge how well the gene tolerates losing a copy. Missense variants: 177 observed, 181.17 expected, observed/expected ratio (o/e) 0.98, 90% interval 0.86 to 1.11. Synonymous variants: 104 observed, 86.86 expected, observed/expected ratio (o/e) 1.2, 90% interval 1.02 to 1.41.
Homologues: Orthologues: chimpanzee PHLDA3 (100% identical), macaque PHLDA3 (100% identical), guinea pig PHLDA3 (98% identical), mouse Phlda3 (98% identical), rabbit PHLDA3 (98% identical), rat Phlda3 (98% identical), dog PHLDA3 (97% identical), pig PHLDA3 (94% identical), zebrafish phlda3 (46% identical). Paralogues in human: PHLDA1 (51% identical), PHLDA2 (47% identical).
Diseases named in the same sentence as PHLDA3 in open-access papers:
PHLDA3 is named in the same sentence as 52 diseases in open-access papers, as found by Europe PMC text mining. Sharing a sentence is not in itself a finding about the gene and the disease. The quoted sentences say what the papers report.
pancreatic neuroendocrine tumor (7 papers, 2017 to 2026). Pancreatic endocrine tumor, also known as pancreatic neuroendocrine tumor (PNET), describes a group of endocrine tumors originating in the pancreas that are usually indolent and benign, but may have the potential to be malignant. "Loss of heterozygosity (LOH) at the PHLDA3 gene locus is linked to the progress and malignant phenotype of pancreatic neuroendocrine tumors (PanNETs)." (PMID 35112982, 2022). "Recent investigations have linked PHLDA3 as a tumor repressor gene to diverse cancers, for instance prostate cancer, pancreatic neuroendocrine tumors, as well as breast cancer." (PMID 35112982, 2022). "PHLDA3 status has also been reported to be associated with clinical outcome in pancreatic NET patients." (PMID 30787304, 2019). "Recently, we have reported that PHLDA3 is a novel tumor suppressor and loss of PHLDA3 heterozygosity is associated with poorer prognosis in pancreatic NET patients." (PMID 30787304, 2019). "Recently, we reported that in pancreatic NET patients, a loss of heterozygosity (LOH) in PHLDA3 was associated with poorer prognosis, and that LOH of both PHLDA3 and MEN1 was frequently observed." (PMID 30787304, 2019). "MEN1 is another tumor suppressor gene frequently inactivated in pancreatic NET, and we previously observed that double loss of heterozygosity (LOH) of PHLDA3 and MEN1 frequently occurs in pancreatic NET8,9." (PMID 30787304, 2019). "We also analyzed LOH of PHLDA3 and MEN1, two tumor suppressor genes frequently inactivated in pancreatic NETs." (PMID 30787304, 2019).
esophageal squamous cell carcinoma (4 papers, 2020 to 2025). Esophageal squamous cell carcinoma (ESCC) is a type of esophageal carcinoma (EC) that can affect any part of the esophagus, but is usually located in the upper or middle third. "Previous studies have linked low expression of PHLDA3 to poor prognosis in esophageal squamous cell carcinoma." (PMID 41289299, 2025). "Although documented PHLDA3 KO cases are limited, we did find the association between low PHLDA3 protein levels and poor cancer-specific and disease-free survival in 26% esophageal squamous cell carcinoma patients." (PMID 32312982, 2020). "PHLDA3 indicates poor prognosis in patients with esophageal squamous cell carcinoma." (PMID 38921000, 2024).
lung carcinoma (4 papers, 2018 to 2024). "For PHLDA3, from a research article, it is clear that this gene is upregulated in kidney cancer and that this gene is mutated in lung cancer." (PMID 38921000, 2024). "Since PHLDA3 is a repressor of Akt, it is conceivable that functional loss of PHLDA3 could contribute to the tumorigenesis and development of lung cancers." (PMID 32521808, 2020). "We analyzed various types of lung cancers and found a high frequency of PHLDA3 gene defects in lung NETs compared to other types of lung cancer." (PMID 32521808, 2020). "PHLDA3 was previously shown to function as a unique AKT inhibitor through the depletion of membrane-bound phosphatidyl inositols, however, the physiological function of PHLDA2 in lung cancer has not been defined." (PMID 29861842, 2018).
lung NETs (4 papers, 2020 to 2025). "A study discovered a significant prevalence of PHLDA3 gene abnormalities in lung neuroendocrine tumors (LNETs), particularly in comparison to other forms of lung cancer." (PMID 40227573, 2025). "In lung neuroendocrine tumors (NETs), PHLDA3 promoter methylation has been identified as a key mechanism responsible for its downregulation." (PMID 40227573, 2025). "Since the PHLDA3 gene is located at 1q31 and LOH at the PHLDA3 gene locus is frequently found in lung NETs, we speculated that the PHLDA3 gene may also undergo LOH in PanNETs." (PMID 32521808, 2020). "For example, PHLDA3 is inactivated by both LOH and methylation in various neuroendocrine tumors (NETs), such as Lung NETs and PanNETs." (PMID 35112982, 2022).
lymphoma (4 papers, 2023 to 2025). A malignant (clonal) proliferation of B- lymphocytes or T- lymphocytes which involves the lymph nodes, bone marrow and/or extranodal sites. "However, WES data reveal that the suppression of Phlda3 mRNA in Phlda3+/− lymphomas cannot be explained by somatic mutations or copy number changes." (PMID 37558703, 2023). "Remarkably, whole-exome sequencing data showed that lymphomas in irradiated Phlda3+/+ mice harbor a significantly higher number of single nucleotide variants (SNVs) and indels compared to lymphomas in irradiated Phlda3+/− and Phlda3−/− littermates." (PMID 37558703, 2023). "We next explored whether loss of Phlda3 affects the number of genomic alterations in radiation-induced lymphomas." (PMID 37558703, 2023). "Interestingly, despite the induction of PHLDA3 protein expression by radiation, deletion of the PHLDA3 gene did not alleviate the acute hematopoietic toxicity caused by radiation exposure or protect against radiation injury or the development of lymphoma." (PMID 40227573, 2025). "The pattern of PHLDA3 is overexpressed in cholangiocarcinoma, brain cancers, kidney cancers, testicular cancer, and lymphoma; however, it has lower expression in colon, esophageal, sarcoma, and stomach cancers." (PMID 38921000, 2024). "Our findings from WES show that lymphomas in irradiated Phlda3+/+ mice harbor a significantly higher number of SNVs and indels compared to lymphomas in irradiated Phlda3+/− and Phlda3−/− littermates." (PMID 37558703, 2023). "Among the novel N3a-sensitive PI3K/mTOR-reducing proteins in lymphomas, were increased PHLDA3 (R_cHL/MCL), OSMR (R_cHL), COL6A3, and Rictor (P_ALCL/cHL)." (PMID 37568720, 2023). "The fact that both Phlda3−/− and Phlda3+/− lymphomas showed a distinct phenotype compared to Phlda3+/+ lymphomas prompted us to examine the expression of Phlda3 mRNA in these tumors." (PMID 37558703, 2023). "Unexpectedly, we noticed that the expression of Phlda3 mRNA in Phlda3+/− lymphomas was approximately 20 folds lower compared to which in Phlda3+/+ lymphomas." (PMID 37558703, 2023). "We observed significantly more SNVs and indels in Phlda3+/+ compared with Phlda3−/− and Phlda3+/− lymphomas." (PMID 37558703, 2023). "Additionally, altered PHLDA3 expression in lymphomas suggests its potential role in post-radiation malignancies." (PMID 40227573, 2025). "On the other hand, PHLDA3 is observed in brain, lymphoma, kidney, and cholangiocarcinoma cancers." (PMID 38921000, 2024). "Similarly, we did not observe any significant differences in COSMIC Tier 1 genes affected by SNVs/indels or SCNAs between lymphomas in Phlda3−/−, Phlda3+/−, and Phlda3+/+ mice." (PMID 37558703, 2023). "We observed that Phlda3 is not expressed in Phlda3−/− lymphomas, which confirmed the complete loss of the Phlda3 gene in these tumors." (PMID 37558703, 2023). "However, SCNA analysis indicated that the substantial decrease in mRNA expression of Phlda3 in Phlda3+/− lymphomas cannot be explained by copy number alterations of Phlda3." (PMID 37558703, 2023). "Of note, we did not observe Phlda3 mutations in any of the lymphomas." (PMID 37558703, 2023). "To explore whether loss of Phlda3 affects the mutational spectrum within radiation-induced thymic lymphomas, we performed whole-exome sequencing of radiation-induced lymphomas from Phlda3−/−, Phlda3+/−, and Phlda3+/+ (WT) mice and identified SNVs, indels, and SCNAs." (PMID 37558703, 2023). "Indeed, gene expression analysis shows that the expression of Phlda3 mRNA in Phlda3+/− lymphomas is not significantly higher than in Phlda3−/− lymphomas." (PMID 37558703, 2023).
neuroendocrine tumors (3 papers, 2020 to 2025). "In this review, we will focus on PHLDA3, a tumor suppressor gene that encodes a repressor of the Akt oncoprotein and is important for the development of neuroendocrine tumors (NETs)." (PMID 32521808, 2020). "PHLDA3 mRNA levels have been shown to correlate with prognosis in various cancers, including SCC and neuroendocrine tumors, where reduced levels indicate poorer outcomes." (PMID 40227573, 2025).
prostate carcinoma (3 papers, 2020 to 2025). A carcinoma that arises from epithelial cells of the prostate gland. "In prostate cancer, 22% of patients exhibit decreased PHLDA3 expression, with clinical recurrence associated with significant DNA methylation of the PHLDA3 gene." (PMID 40227573, 2025). "Moreover, PHLDA3 has been shown to exert anti-tumor effects in prostate cancer by downregulating the Wnt/β-catenin pathway through inhibition of Akt." (PMID 41289299, 2025). "The promoter region of PHLDA3 is highly methylated in prostate cancer." (PMID 40227573, 2025). "Moreover, a study reported that in prostate cancer cell lines, PHLDA3 levels are low." (PMID 40227573, 2025). "Tumor-suppressive roles of PHLDA3 protein have been reported in several cancer cell lines including ESCC, osteosarcoma (OS), acute myeloid leukemia (AML), B-cell lymphoma, and prostate cancer." (PMID 40227573, 2025). "Similarly, the PHLDA3 mRNA and protein levels were increased upon G6PD knockdown and decreased upon G6PD overexpression in the human PTEN null PC3 prostate cancer cells, indicating that PHLDA3 expression is negatively regulated by the PPP." (PMID 32312982, 2020).
acute myeloid leukemia (2 papers, 2023 to 2025). Acute myeloid leukemia (AML) is a group of neoplasms arising from precursor cells committed to the myeloid cell-line differentiation.
amyotrophic lateral sclerosis (2 papers, 2024 to 2025). Amyotrophic lateral sclerosis (ALS) is a neurodegenerative disease characterized by progressive muscular paralysis reflecting degeneration of motor neurons in the primary motor cortex, corticospinal tracts, brainstem and spinal cord. "A recent study indicates that PHLDA3 expression is significantly upregulated in astrocytes derived from amyotrophic lateral sclerosis (ALS) patients, where it promotes cellular stress responses by increasing reactive oxygen species (ROS) concentrations." (PMID 41289299, 2025).
colon carcinoma (2 papers, 2023 to 2024). "Moreover, liver and colon cancer survival rates were positively linked with upregulated PHLDA3 levels." (PMID 38921000, 2024).
osteosarcoma (2 papers, 2022 to 2025). A usually aggressive malignant bone-forming mesenchymal neoplasm, predominantly affecting adolescents and young adults. "According to the bioinformatics analysis, PHLDA3 expression was low in osteosarcoma patients, and low content was linked to poor prognosis." (PMID 35112982, 2022). "Additionally, activation of PHLDA3 suppressed osteosarcoma cell proliferation, migration, and chemoresistance, whereas PHLDA3 inhibition caused the opposite effects." (PMID 35112982, 2022). "Mechanistically, our data revealed that PHLDA3 negatively regulates the Akt/GSK3β signaling cascade in osteosarcoma." (PMID 35112982, 2022). "Herein, we purposed to elucidate the role of PHLDA3 in the progression and chemoresistance of osteosarcoma." (PMID 35112982, 2022). "We verified that PHLDA3 played a tumor suppressor role in osteosarcoma and suppressed cell proliferation, migration and enhanced cisplatin-induced cell apoptosis via regulating the Akt/ GSK-3β signaling pathway." (PMID 35112982, 2022). "In this study, we explored the role of PHLDA3 in osteosarcoma and investigated the involvement of potential signaling pathway." (PMID 35112982, 2022). "Furthermore, we found that miR-19a-3p might exert its oncogenic function by inhibiting PHLDA3 expression in osteosarcoma." (PMID 35112982, 2022). "Nevertheless, the expression and role of PHLDA3 in osteosarcoma remain unknown." (PMID 35112982, 2022).
rectal NET (2 papers, 2019 to 2020). "Functional loss of PHLDA3 is found in PanNETs, and LOH at PHLDA3 locus is frequently found in lung and rectal NETs." (PMID 32521808, 2020). "PHLDA3 has been found to be functionally deficient not only in PanNETs but also in lung NETs and rectal NETs, suggesting that it may be a common tumor suppressor of NETs." (PMID 32521808, 2020). "It is likely that LOH of PHLDA3 in rectal NETs results in the production of some tumor promoting factors, but further study will be required to confirm this." (PMID 30787304, 2019). "Thus, similar to PanNETs, the tumor suppressing pathways involving PHLDA3 and MEN1 are distinct in rectal NETs, and their development involves the functional loss of both pathways." (PMID 32521808, 2020). "Therefore, PHLDA3 and MEN1 LOH were also assessed in rectal NET patients for their association with clinicopathological features." (PMID 30787304, 2019). "While the role of PHLDA3 in carcinogenesis is less clear, higher level of epigenetic alterations in normal tissues may also be found in rectal NETs patients." (PMID 30787304, 2019). "We report here the novel finding that LOH occurs at the PHLDA3 and MEN1 loci in 60.0% and 66.7% of rectal NETs cases, respectively." (PMID 30787304, 2019). "The strikingly high incidence of LOH at these loci indicates that PHLDA3 and MEN1 are important in tumor suppression in rectal NETs." (PMID 30787304, 2019).
sarcoma (2 papers, 2022 to 2024). A usually aggressive malignant neoplasm of the soft tissue or bone. "In gastric, ovarian, sarcoma, and uterine cancer, we found a direct link between PHLDA3 overexpression and poor patient survival." (PMID 38921000, 2024).
squamous cell carcinoma (2 papers, 2022 to 2025). A carcinoma arising from squamous epithelial cells. "For example, decreased PHLDA3 expression was remarkably linked to tumor progress along with recurrence in individuals with squamous cell carcinomas, indicating a poor prognosis." (PMID 35112982, 2022). "Downregulation of PHLDA3 is associated with increased mesenchymal EMT marker expression, higher metastatic potential, and accelerated cancer progression in squamous cell carcinomas (SCC)." (PMID 40227573, 2025).
acute kidney injury (1 paper, 2022). Sudden and sustained deterioration of the kidney function characterized by decreased glomerular filtration rate, increased serum creatinine or oliguria. "Moreover, several studies have demonstrated that PHLDA3 is differentially expressed in cisplatin-induced acute kidney injury patients." (PMID 35112982, 2022).
B-cell lymphoma (1 paper, 2025). "PHLDA3 significantly impacts the B-cell receptor (BCR) signaling pathway in the context of B-cell lymphoma." (PMID 40227573, 2025).
bladder cancer (1 paper, 2024). "In bladder cancer, PHLDA3 mutations primarily occurred and spread throughout the plekstrin domain, with an E82K/G/D hotspot." (PMID 38921000, 2024).
brain cancer (1 paper, 2024). A primary or metastatic malignant neoplasm affecting the brain. "Moreover, in general, any deviation in PHLDA3 expression, when compared to the expression mark observed in normal tissues, was associated with poor prognosis in breast and brain cancer." (PMID 38921000, 2024).
cataract (1 paper, 2017). Partial or complete opacity of the crystalline lens of one or both eyes that decreases visual acuity and eventually results in blindness.
cholangiocarcinoma (1 paper, 2024). A carcinoma that arises from the intrahepatic biliary tree (intrahepatic cholangiocarcinoma) or from the junction, or adjacent to the junction, of the right and left hepatic ducts (hilar cholangiocarcinoma). "In stomach (STAD), kidney (KICH), lung (LUAD), and cholangiocarcinoma (CHOL) tumors, we found that PHLDA3 expression is positively linked with 2236, 4092, 2562, and 6889 genes, respectively." (PMID 38921000, 2024).